CST4 (cystatin S)
Description:
This protein strongly inhibits papain and ficin, partially inhibits stem bromelain and bovine cathepsin C, but does not inhibit porcine cathepsin B or clostripain. Papain is inhibited non-competitively.
Tractability: Antibody: UniProt places it where antibodies can reach, with high confidence; UniProt predicts a signal peptide or a membrane-spanning region; its Gene Ontology location is reachable by antibodies, with medium confidence.
Gene: Protein-coding gene on chromosome 20 (23,685,640 to 23,689,038, reverse strand). Ensembl gene ENSG00000101441.
Subcellular location: Secreted
Gene Ontology:
Molecular function: cysteine-type endopeptidase inhibitor activity; protein binding
Biological process: detection of chemical stimulus involved in sensory perception of bitter taste; negative regulation of proteolysis
Cellular component: extracellular exosome; extracellular region; cytoplasm; vesicle
Genetic constraint (gnomAD): Loss-of-function variants: 17 observed, 12.46 expected, observed/expected ratio (o/e) 1.36, 90% interval 0.93 to 1.87. The upper end of that interval is the gene's LOEUF score, 1.87, which puts it in group 6 of 6, group 1 being the genes least tolerant of losing a copy. Missense variants: 251 observed, 184.11 expected, observed/expected ratio (o/e) 1.36, 90% interval 1.23 to 1.51. Synonymous variants: 93 observed, 71.75 expected, observed/expected ratio (o/e) 1.3, 90% interval 1.1 to 1.54.
Homologues: Orthologues: macaque CST2 (84% identical), zebrafish si:busm1-57f23.1 (23% identical), Caenorhabditis elegans cpi-1 (20% identical), Caenorhabditis elegans cpi-2 (18% identical), Caenorhabditis elegans K08B4.7 (9% identical). Paralogues in human: CST2 (88% identical), CST1 (87% identical), CST3 (57% identical), CST5 (55% identical), CST6 (31% identical), CST8 (28% identical), CST7 (26% identical), CSTL1 (26% identical), CST9L (25% identical), CST11 (24% identical), CST9 (21% identical).